APMAP (adipocyte plasma membrane associated protein)
Description:
Exhibits strong arylesterase activity with beta-naphthyl acetate and phenyl acetate. May play a role in adipocyte differentiation.
Synonyms: C20orf3; BSCv
Tractability: Antibody: UniProt predicts a signal peptide or a membrane-spanning region; the Human Protein Atlas places it where antibodies can reach. PROTAC: ubiquitination databases record sites on it; its protein half-life has been measured.
Gene: Protein-coding gene on chromosome 20 (24,962,925 to 24,992,782, reverse strand). Ensembl gene ENSG00000101474.
Subcellular location: Membrane
Subcellular location (Human Protein Atlas): Plasma membrane
Gene Ontology:
Molecular function: arylesterase activity; protein binding
Cellular component: cell surface; membrane
Genetic constraint (gnomAD): Loss-of-function variants: 33 observed, 38.7 expected, observed/expected ratio (o/e) 0.85, 90% interval 0.64 to 1.14. The upper end of that interval is the gene's LOEUF score, 1.14, which puts it in group 4 of 6, group 1 being the genes least tolerant of losing a copy. Missense variants: 485 observed, 535.41 expected, observed/expected ratio (o/e) 0.91, 90% interval 0.84 to 0.98. Synonymous variants: 222 observed, 219.58 expected, observed/expected ratio (o/e) 1.01, 90% interval 0.9 to 1.13.
Homologues: Orthologues: chimpanzee APMAP (99% identical), pig APMAP (90% identical), mouse Apmap (89% identical), guinea pig APMAP (89% identical), macaque APMAP (86% identical), rat Apmap (80% identical), rabbit APMAP (78% identical), zebrafish apmap (65% identical), Caenorhabditis elegans T12G3.4 (32% identical), Caenorhabditis elegans F57C2.5 (31% identical), Drosophila melanogaster Ssl2 (31% identical), Drosophila melanogaster Hmu (29% identical), and 1 more.
Diseases named in the same sentence as APMAP in open-access papers:
APMAP is named in the same sentence as 31 diseases in open-access papers, as found by Europe PMC text mining. Sharing a sentence is not in itself a finding about the gene and the disease. The quoted sentences say what the papers report.
prostate carcinoma (5 papers, 2021 to 2026). A carcinoma that arises from epithelial cells of the prostate gland. "Adipocyte plasma membrane-associated protein (APMAP) interacts with ESP15R and activates the EGFR-ERK1/2 pathway, thereby initiating EMT in prostate cancer cells." (PMID 41596341, 2026). "The APMAP/EGFR axis enhances cholesterol-induced EMT in prostatic carcinoma, and APMAP promotes metastasis of cervical cancer by activating the Wnt/β-catenin pathway." (PMID 40821803, 2025). "APMAP has been reported to be involved in lipid transport and can induce epithelial-mesenchymal transition of prostate cancer and the liver metastasis of colorectal cancer." (PMID 34539899, 2021). "In parallel, related to prostate cancer, cholesterol could control EMT through its binding to the adipocyte plasma membrane-associated protein (APMAP)." (PMID 39199549, 2024). "High cholesterol-mediated upregulation of adipocyte plasma membrane-associated protein (APMAP) in cholesterol-induced lipid rafts inhibits EGFR degradation, thereby activating the extracellular-regulated protein kinase 1/2 (ERK1/2) pathway and inducing EMT in prostate cancer cells." (PMID 38617549, 2024). "APMAP is characterized as a transmembrane protein and can induce EMT in prostate cancer and liver metastasis in colorectal cancer." (PMID 40821803, 2025). "APMAP is upregulated by cholesterol and is involved in EMT progression as well as metastasis in prostate cancer." (PMID 34539899, 2021).
cervical cancer (3 papers, 2021 to 2025). A primary or metastatic malignant neoplasm involving the cervix. "In this study, we identified that Adipocyte Plasma Membrane-Associated Protein (APMAP) was closely associated with cervical cancer cell migration." (PMID 34539899, 2021). "Six interesting core DEPs (SPARC, HPX, VCAM1, TFRC, ERN1 and APMAP) were confirmed to be potential plasma diagnostic markers for LVSI and LNM in cervical cancer patients." (PMID 37689639, 2023). "Compared with the negative control group, the protein levels of β-catenin in the APMAP knockdown group decreased and the protein levels of p-GSK3β/GSK3β increased in the three types of cervical cancer cells." (PMID 34539899, 2021). "Mechanically, APMAP promotes cervical cancer cell migration and epithelial-mesenchymal transition by activating the Wnt/β-catenin pathway." (PMID 34539899, 2021). "For survival analysis, among the 197 cervical cancer patients in the TCGA database, patients with higher APMAP mRNA levels had a relatively shorter survival time compared to those with lower APMAP mRNA levels (P < 0.05)." (PMID 34539899, 2021). "We identified 20 differential genes including APMAP that were involved in epithelial cell differentiation during the progression of cervical cancer." (PMID 34539899, 2021). "These rescue results indicated the Wnt/β-catenin pathway played a major role in APMAP promoting the migration of cervical cancer cells." (PMID 34539899, 2021). "Our Western blotting experiment revealed that APMAP knockdown inhibited the EMT process of cervical cancer cells, which decreased the protein expressions of snail, N-cadherin and vimentin, and increased the protein E-cadherin." (PMID 34539899, 2021). "We found that APMAP was highly expressed in cervical cancer tissues, and patients with high expression had poor prognosis." (PMID 34539899, 2021). "We identified that APMAP promotes cervical cancer cell migration and epithelial-mesenchymal transition by activating the Wnt/β-catenin pathway, which provides new understanding of the role of APMAP in tumor research." (PMID 34539899, 2021). "When APMAP was knocked down, the ability of the cervical cancer cells to migrate was greatly inhibited." (PMID 34539899, 2021). "We also found that the expression of APMAP in cervical cancer tissues was higher than in normal tissues, and the high expression of APMAP had a poor prognosis." (PMID 34539899, 2021). "In conclusion, for the first time, we explored the functional role and molecular mechanism of APMAP in cervical cancer." (PMID 34539899, 2021). "The functional in vitro experiments demonstrated that APMAP knockdown significantly inhibited the migration ability of cervical cancer cells, but had little effect on cell apoptosis." (PMID 34539899, 2021). "In addition to the discovery that APMAP affects the migration of cervical cancer cells, we also found that APMAP was highly expressed in the cancer tissues of cervical cancer patients." (PMID 34539899, 2021). "Our study demonstrated that APMAP may promote cervical cancer cell migration and epithelial-mesenchymal transition by activating the Wnt/β-catenin pathway." (PMID 34539899, 2021). "Overall, APMAP is a potential prognostic marker as well as a therapeutic target of cervical cancer." (PMID 34539899, 2021). "Using bioinformatics and proteomic sequencing analysis, we found that APMAP may play an important function in cervical cancer." (PMID 34539899, 2021). "Patients with high expression of APMAP had poor prognosis, while patients with low expression of APMAP had good prognosis, which indicates that APMAP can be used as a prognostic biomarker for patients with cervical cancer." (PMID 34539899, 2021). "APMAP promotes the EMT and metastasis of cervical cancer cells by activating the Wnt/β-catenin pathway, and ERN1 is related to the apoptosis of cervical cancer cells." (PMID 37689639, 2023). "However, the role of APMAP in cervical cancer is still unknown." (PMID 34539899, 2021).
cervical cancer (continued). "However, it is unknown whether APMAP plays a role in cervical cancer." (PMID 34539899, 2021). "There was a significant difference in the migration ability between the APMAP knockdown group and the negative control group in HeLa, Caski and Siha cervical cancer cells." (PMID 34539899, 2021). "To verify whether APMAP promoted the migration and EMT of cervical cancer cells through the Wnt/β-catenin pathway, we used the β-catenin agonist SKL2001 to activate β-catenin in the APMAP knockdown cells." (PMID 34539899, 2021).
lung carcinoma (3 papers, 2021 to 2025). "The expression levels of seven proteins (CD5L, CLEC3B, SERFINF1, ITIH4, SAA4, SERFINC1, and C20ORF3 (APMAP)) were found to be significantly increased in serum-derived EVs of lung cancer patients, including AC, SCC, and small cell lung cancer (SCLC)." (PMID 35158999, 2022).
Obesity (3 papers, 2017 to 2021). Accumulation of substantial excess body fat. "This suggests that APMAP is a key regulator providing the association between high-fat diet, obesity, and metastasis." (PMID 34539899, 2021). "In this study, we concentrated on the physiologic characterization of adipocyte plasmamembrane–associated protein (APMAP) in the context of obesity." (PMID 28559441, 2017). "APMAP is a novel regulator of ECM components that may serve as a potential target to mitigate obesity-associated insulin resistance." (PMID 32792973, 2020). "Here we provide the first evidence that APMAP is involved in regulating adiposecomposition and consequently metabolic health in obesity." (PMID 28559441, 2017).
Alzheimer disease (2 papers, 2019 to 2025). A progressive, neurodegenerative disease characterized by loss of function and death of nerve cells in several areas of the brain leading to loss of cognitive function such as memory and language. "APMAP is widely distributed in mammals and has been demonstrated to be associated with various diseases, including gestational diabetes mellitus, polycystic ovary syndrome, primary Sjogren’s syndrome, demyelinating disease and Alzheimer’s disease." (PMID 40693273, 2025). "The adipocyte plasma membrane-associated protein APMAP is expressed in the brain where it associates with γ-secretase, a protease responsible for the generation of the amyloid-β peptides (Aβ) implicated in the pathogenesis of Alzheimer’s disease (AD)." (PMID 30704515, 2019).
colorectal cancer (2 papers, 2021 to 2025). A primary or metastatic malignant neoplasm that affects the colon or rectum. "This indicated that APMAP may be used as a biomarker to determine the prognosis of liver metastasis from colorectal cancer." (PMID 34539899, 2021). "Another clinical study noted that APMAP expression was higher in the tissues of colorectal cancer patients with liver metastasis than in patients without metastasis." (PMID 34539899, 2021).
HCMV infection (2 papers, 2019 to 2022). "Dramatically reduced immediate early gene (IE) transcription and delayed nuclear translocation of tegument protein pp65 were detected in APMAP-deficient cells at early stage HCMV infection." (PMID 31356650, 2019). "We report here identification of a type II membrane protein, adipocyte plasma membrane associated protein (APMAP), as a novel modulator promoting HCMV infection." (PMID 31356650, 2019). "Taken together, these results demonstrate that HCMV infection is inhibited in ARPE-19 cells with deficient APMAP expression." (PMID 31356650, 2019). "Here we report identification of adipocyte plasma membrane-associated protein (APMAP) as a novel modulator active in the early stage of HCMV infection." (PMID 31356650, 2019). "APMAP deficiency caused significantly lower HCMV infection in both epithelial and fibroblast cells while over-expression of APMAP increased HCMV infection of less susceptible cells, all in a pentamer non-specific manner." (PMID 31356650, 2019). "Although no significant decrease in HCMV attachment and viral internalization was observed between APMAP deficient versus wildtype cells, APMAP deficiency was correlated with lower nuclear translocation of pp65 and lower IE mRNA level at the early stage of HCMV infection." (PMID 31356650, 2019). "Further investigations are needed to identify the mechanism by which APMAP affects low pH-dependent or -independent HCMV infection." (PMID 31356650, 2019). "We demonstrated that APMAP is both necessary and sufficient for HCMV infection of multiple cell types." (PMID 31356650, 2019). "One of the candidate proteins, adipocyte plasma membrane associated protein (APMAP), was found necessary for HCMV infection in epithelial cells and fibroblast cells." (PMID 31356650, 2019). "Further efforts are needed to clearly define the mechanism of APMAP in HCMV infection of different cells." (PMID 31356650, 2019). "Taken together, our results suggest that APMAP functions as a modulator promoting HCMV infection in multiple cell types and is an important player in the complex HCMV infection mechanism." (PMID 31356650, 2019). "APMAP is necessary for HCMV infection in both epithelial cells and fibroblasts; knockdown of APMAP expression significantly reduced HCMV infection of these cells." (PMID 31356650, 2019). "Consistent with the results in APMAP K/O ARPE-19 cells, knockdown of APMAP expression significantly reduced HCMV infection in HepG2 and Hela cells and HCMV infection in MRC-5 cells." (PMID 31356650, 2019). "The stable clones with APMAP gene knockout showed the lowest levels of IE protein expression, correlated with the most pronounced effect on HCMV infection." (PMID 31356650, 2019). "Taken together, our results indicated that APMAP is a cellular factor augmenting HCMV infection at the early stage of viral infection." (PMID 31356650, 2019). "To further understand the role of APMAP in HCMV infection, we monitored the internalization of HCMV at different times after infection." (PMID 31356650, 2019). "Taken together, these results indicated that APMAP is necessary for HCMV infection of human epithelial cells." (PMID 31356650, 2019). "Furthermore, results of multiple experiments demonstrated significantly reduced HCMV infection in the ARPE-19 cells with defect APMAP expression." (PMID 31356650, 2019). "In summary, APMAP was identified as a novel modulator active at an early stage of HCMV infection." (PMID 31356650, 2019). "APMAP could have a role in HCMV infection through interaction with gH/gL containing glycoprotein complexes at low pH or through mediating nucleus translocation of pp65." (PMID 31356650, 2019). "Results from biochemical studies of APMAP and HCMV proteins suggest that APMAP could participate in HCMV infection through interaction with gH/gL containing glycoprotein complexes at low pH and mediate nucleus translocation of tegument pp65." (PMID 31356650, 2019).
HCMV infection (continued). "Interestingly, over-expression of APMAP not only enhanced HCMV infection in human cells but also promoted HCMV entry in less susceptible canine MDCK and murine NIH/3T3 cells." (PMID 31356650, 2019). "Next, we sought to confirm the effect of reduced expression of APMAP on HCMV infection." (PMID 31356650, 2019). "Taken together, our results implicate APMAP as a broad modulator at early stage HCMV infection." (PMID 31356650, 2019). "Further studies are needed to address the question of whether APMAP is important for HCMV infection of monocytes, myeloid lineage cells, or other primary cells." (PMID 31356650, 2019). "Over-expression of human APMAP promoted HCMV infection of two non-human cell types less susceptible to HCMV entry, canine MDCK and murine NIH/3T3 cells." (PMID 31356650, 2019). "In this study, APMAP was identified as a novel modulator in the early stage of HCMV infection." (PMID 31356650, 2019). "Thus, APMAP is necessary for HCMV infection in multiple cell lines." (PMID 31356650, 2019). "Therefore, APMAP was chosen for further studies of its role in HCMV infection." (PMID 31356650, 2019). "The in vitro interaction between APMAP and HCMV proteins by biochemical assays supported the notion that APMAP may participate in HCMV infection through interaction with gH/gL containing glycoprotein complexes at low pH and through mediating nuclear translocation of pp65." (PMID 31356650, 2019). "Our data have shown that knockdown APMAP inhibits HCMV infection and overexpression of APMAP enhances HCMV infection." (PMID 31356650, 2019). "The entry of both AD169-GFP and AD169rev-GFP were affected in APMAP K/D MRC-5 cells, suggesting that APMAP is not involved in HCMV infection in a pentamer specific manner." (PMID 31356650, 2019). "Efficient nuclear translocation of pp65 at early stage HCMV infection was detected in wildtype ARPE-19 and MRC-5 cells but not in APMAP deficient cells." (PMID 31356650, 2019). "Interestingly, ectopic expression of human APMAP in cells refractory to HCMV infection, such as canine MDCK and murine NIH/3T3 cells, promoted HCMV infection." (PMID 31356650, 2019). "In addition, human APMAP was overexpressed in the mouse fibroblast cell line NIH/3T3, which is not susceptible to HCMV infection." (PMID 31356650, 2019). "Two non-human cell lines were selected to test whether human APMAP can enhance HCMV infection." (PMID 31356650, 2019).
Insulin resistance (2 papers, 2020 to 2023). Increased resistance towards insulin, that is, diminished effectiveness of insulin in reducing blood glucose levels. "APMAP caused insulin resistance through IRS-1/insulin sensitive genes/free fatty acids pathway." (PMID 36766716, 2023).
polycystic ovary syndrome (2 papers, 2020 to 2025). A disorder that manifests as multiple cysts on the ovaries. "In human ffEVs, 86 proteins were differentially expressed in patients with polycystic ovary syndrome relative to controls, some of which were also identified in our study (APMAP, PRDX6, isocitrate and malate dehydrogenases, etc)." (PMID 33330709, 2020).
viral infection (2 papers, 2019 to 2020). "At this early stage, JCPyV may also interact with adipocyte plasma membrane associated protein (APMAP), a surface protein found in glial cells and throughout the body which appears to be important for productive viral infection." (PMID 32882975, 2020). "We next sought to determine the function of APMAP in pentamer-associated viral infection." (PMID 31356650, 2019). "Taken together, our results indicate that APMAP serves as an augmenting modulator of HCMV at the early stage of viral infection." (PMID 31356650, 2019). "The infectivity of AD169rev-GFP as indicated by the number of GFP positive cells and IE mRNA levels at 48 h after virus infection (MOI = 1.0) were also significantly decreased in APMAP K/D cells than in wildtype Hela cells and Hela cells with sc-shRNA." (PMID 31356650, 2019). "In addition, pre-incubation of soluble APMAP-Fc with AD169rev-GFP exhibited marginally inhibiting effect on virus infection in ARPE-19 cells." (PMID 31356650, 2019). "However, results indicate a significant role for APMAP in viral entry at the early stage of viral infection for the cell types tested." (PMID 31356650, 2019).
Anxiety (1 paper, 2019). Intense feelings of nervousness, tension, or panic often arise in response to interpersonal stresses. "Moreover, APMAP deletion did not affect anxiety, mobility, or exploratory drive, as estimated in the elevated plus maze and open field tests." (PMID 30704515, 2019).
Delusion (1 paper, 2021). A delusion is a fixed false belief held despite evidence to the contrary. "Furthermore, six autoantibodies were associated with specific psychopathology symptoms: anti-AP3B2 (persecutory delusions), anti-TDO2 (hallucinations), anti-CRYGN (initial insomnia); anti-APMAP (poor appetite), anti-OLFM1 (above-median cognitive function), and anti-WHAMMP3 (anhedonia and dysphoria)." (PMID 34518517, 2021).
esophageal cancer (1 paper, 2025). A primary or metastatic malignant neoplasm involving the esophagus. "Further analysis of the UALCAN database revealed significant upregulation of APMAP in esophageal cancer, and the increased mRNA and protein expression levels of APMAP were also detected in three ESCC cell lines compared with HEEC cells." (PMID 40821803, 2025).